ATRX (ATRX chromatin remodeler)
Diseases named in the same sentence as ATRX in open-access papers (continued):
Sharing a sentence is not in itself a finding about the gene and the disease.
sarcoma (continued). "However, genes down-expressed by ATRX-altered poorly differentiated pleomorphic sarcomas are mostly linked to adaptive immune cell activation, so adaptive immune cells are either less present or less active." (PMID 33946962, 2021). "DAXX and ATRX may be also mutated in different types of sarcomas." (PMID 30871494, 2019). "Consistent with the overall cohort, the most frequently mutated DDR pathway gene was ATRX (20/446, 4.3%), which was observed in 9 sarcoma subtypes (2.4–15.8% ATRX-mut)." (PMID 40563612, 2025). "To date, no veterinary studies immunohistochemically investigated DAXX or ATRX expression in canine neoplasms other than PanNENs and sarcomas." (PMID 41472189, 2025). "Further research into targeting ATRX should consider multiple sarcomas, particularly leiomyosarcoma, for these therapeutics." (PMID 40563612, 2025). "Within sarcomas, ATRX is altered in more than 10 percent of undifferentiated pleomorphic sarcoma, leiomyosarcoma, myxofibrosarcoma, perivascular epithelioid tumors, pleomorphic liposarcoma and angiosarcoma." (PMID 38477352, 2024). "We performed a retrospective study of sarcomas from an individual institution to evaluate ATRX as a prognosticator in soft tissue sarcoma." (PMID 38741704, 2024). "ATRX mutation is also associated with increased response to radiation and the oncolytic herpes virus treatment talimogene laherparepvec (TVEC) in a sarcoma cell line xenograft model." (PMID 38473300, 2024). "To accomplish this, we performed a retrospective study of sarcomas from an individual institution and their expression of ATRX was quantitatively determined." (PMID 38741704, 2024). "Consistent with our findings in mouse sarcoma cells, the 143B ATRX KO cells were significantly more sensitive to oncolytic herpesvirus than the ATRX WT isogenic counterpart (left and middle bars)." (PMID 37200088, 2023). "Our findings demonstrated that ATRX KO in our mouse sarcoma cell lines resulted in a significant reduction in intracellular cGAMP." (PMID 37200088, 2023). "Here we sought to investigate the genomic determinants of high telomeric content beyond the canonical ATRX/DAXX alterations within our sarcoma dataset." (PMID 37709802, 2023). "In our study, GO pathway enrichment analysis of RNA-Seq did show an upregulation of pathways related to brown fat cell differentiation and lipid catabolism in ATRX-deleted sarcomas." (PMID 37200088, 2023). "In general, DAXX mutations were more commonly reported than ATRX mutations in PanNET [16•, 17, 18••, 19], whereas those affecting ATRX were markedly prominent in sarcomas [11•]." (PMID 34269919, 2021). "RNA sequencing of 60 poorly differentiated pleomorphic sarcomas (cohort 2) from a previously published cohort was reanalyzed, and 10 ATRX-altered tumors (16.7%) were identified." (PMID 33946962, 2021). "In vitro and in vivo models showed that ATRX down-expression increases tumor growth rate and immune escape by decreasing the immunity load of active mast cells in sarcoma tumors." (PMID 33946962, 2021). "In conclusion, ATRX altered sarcomas represent roughly 1⁄4 of LMS and of poorly differentiated sarcomas." (PMID 33946962, 2021). "In general, mutations affecting DAXX are more common in PanNET, whereas those affecting ATRX are markedly prominent in sarcomas." (PMID 30871494, 2019).
sarcoma (continued). "While in PanNET DAXX/ATRX immunohistochemical loss is absolutely associated with ALT+, the situation appears more complex in sarcomas." (PMID 30871494, 2019). "Analyses revealed that the tumors not only harbored mutations characteristic of sarcoma, such as RB1 (50%), ATRX (38%), and FBXW7 (17%) mutations, but also possessed mutations commonly associated with endometrial adenocarcinoma, including PTEN (42%), PIK3CA (42%), and AKT (17%) mutations." (PMID 41181577, 2025). "Similarly, another study reported that reduced ATRX expression accelerates tumor growth and promotes immune escape by decreasing the presence of active mast cells in the sarcoma microenvironment." (PMID 40495762, 2025). "However, while ATRX loss is known to contribute to the alternative lengthening of telomere phenotype in sarcomas, the functions of ATRX in the epigenetic regulation of gene expression and downstream processes in the mesenchymal context is less understood." (PMID 38477352, 2024). "Somatic alterations in ATRX occur in cancers, such as sarcomas." (PMID 38477352, 2024). "First, we tested whether ATRX deletion also increased sensitivity in vitro to TVEC in the human 143B sarcoma cell line." (PMID 37200088, 2023). "However, it was also reported that ATRX/DAXX alterations were not present in all ALT-positive samples, with one study reporting that 45% of ALT-positive sarcoma samples were ATRX intact." (PMID 37709802, 2023). "ATRX-deleted sarcomas have reduced adaptive and innate immune signaling after ionizing radiation." (PMID 37200088, 2023). "Future studies will be needed to determine whether ATRX-mediated effects on viral heterochromatin also contribute to the sensitivity to oncolytic herpesvirus observed in Atrx-deleted sarcoma cells." (PMID 37200088, 2023). "However, in our dataset, only 12.3% of sarcomas harbored ATRX/DAXX alterations (11.4% for ATRX and 0.9% for DAXX), leaving the remaining cases unexplained." (PMID 37709802, 2023). "In our dataset, only 12.3% of sarcomas harbored ATRX/DAXX alterations." (PMID 37709802, 2023). "Among sarcomas, multiple studies reported that a substantial proportion activates the ALT mechanism for telomere elongation, which is associated with the loss of ATRX and DAXX31,35." (PMID 37709802, 2023). "This strategy could be useful in ATRXWT tumors to enhance the anti-tumoral action of mast cells, and in ATRX-altered sarcomas, to enhance mast cell recruitment and activation." (PMID 33946962, 2021). "Interestingly, poorly differentiated pleomorphic sarcomas with ATRX alteration overexpressed genes related to metabolism, whose upregulation is a known hallmark of cancers and supports cell survival and proliferation." (PMID 33946962, 2021). "ATRX knock-down modifies tumor cell proliferation, as confirmed in vivo, where ATRX knock-down tumors grew three-fold faster than controls, and clonogenicity in sarcoma models." (PMID 33946962, 2021). "Here, we investigated whether ATRX might have additional impacts in the oncogenesis of pleomorphic sarcomas beyond its role in the ALT mechanism and show how its involvement in oncogenesis is also linked to differentiation, tumor growth, and immunity." (PMID 33946962, 2021). "To explore these hypotheses, we studied the ATRX status in a second cohort comprising poorly differentiated pleomorphic sarcomas characterized by RNAseq." (PMID 33946962, 2021). "This phenotype is related to the inhibition of mast cell recruitment upon ATRX alteration, which could be targeted to adapt immunotherapy against pleomorphic sarcomas." (PMID 33946962, 2021).
sarcoma (continued). "Changes in ATRX expression, therefore, may be able to serve as a biomarker for MPNSTs and even other types of sarcomas." (PMID 29796169, 2018). "Interestingly, all ALT-positive sarcomas demonstrated a loss of ATRX expression and belonged to non-soft tissue entities." (PMID 41472189, 2025). "This might lead to a better outcome for sarcoma patients in terms of ATRX status." (PMID 33946962, 2021). "Thus, future work will also hinge on whether ATRX is aberrantly lost in other subtypes of sarcomas as well as MPNSTs." (PMID 29796169, 2018). "In sarcomas, TOP3A amplification is a known driver of ALT in ATRX wild-type tumors, and this alteration has also been observed in pediatric HGG." (PMID 41422096, 2025). "To understand the epigenetic role for ATRX in sarcomas, we performed an analysis of H3.3, H3K9me3 and H3K27ac landscapes in two UPS ATRX KO clones and a WT control and determined chromatin accessibility by ATAC-seq." (PMID 38477352, 2024). "Across all sarcoma samples within our screening cohort, samples with alterations in either GID4, RAD51B, POT1, or ATRX had significantly higher telomeric content than WT samples." (PMID 37709802, 2023). "In agreement with previous studies, telomeric content was significantly higher in ATRX altered and POT1 altered sarcomas." (PMID 37709802, 2023). "Herein, we show that ATRX is aberrantly expressed in the majority of MPNSTs and that this aberrant expression is associated with poor overall survival in NF1-associated MPNSTs, which suggests that ATRX expression could be evaluated as a prognostic biomarker for these aggressive sarcomas." (PMID 29796169, 2018). "Intriguingly, Liau and colleagues found that only 20% (3/15) of radiation-associated sarcomas, which can be classified as UPS, or angiosarcoma, or leiomyosarcoma, were ALT+ and none of these tumors showed ATRX loss." (PMID 34069193, 2021). "This in-depth ATRX genetic analysis revealed that ATRX alteration likely affects a quarter of pleomorphic sarcomas, since it was found in 29.8% of LMS and 16.7% of poorly differentiated pleomorphic sarcomas." (PMID 33946962, 2021). "The overall prevalence of ATRX loss in OS, irrespective of TMM, is about 24%, which is consistent with ATRX loss in sarcomas overall." (PMID 34069193, 2021). "We also stimulated the 143B isogenic cell lines with cGAMP and found that the 143B ATRX KO cell line had significantly less expression of IFNB1, suggesting that at least part of the CGAS/STING pathway impairment was occurring downstream of CGAS in our human sarcoma cell lines." (PMID 37200088, 2023). "Since this is particularly relevant as immunotherapies are currently not efficient in pleomorphic sarcomas, we functionally tested the hypothesis that ATRX alteration might modify the anti-tumor immune response." (PMID 33946962, 2021). "This significant difference prompted us to assess whether the proportion of infiltrating mast cells in human sarcomas is also related to ATRX alteration and the absence of ATRX from the nucleus." (PMID 33946962, 2021). "The accumulation of ATRX foci in senescent cells was not sarcoma specific." (PMID 28855512, 2017). "To test whether these findings also held true in human sarcomas, we used our isogenic 143B human sarcoma cell line with or without CRISPR ATRX knockout and assessed IFNB1 expression levels after treatment with oHSV-60, a 60-bp DNA sequence known to potently stimulate the CGAS/STING pathway." (PMID 37200088, 2023).
sarcoma (continued). "Interestingly, however, survival was similar for patients with sarcomas with and without ATRX alterations when all patients were treated with radiation therapy, suggesting that a ATRX loss-of-function mutation may increase the radiation response of soft tissue sarcomas." (PMID 37200088, 2023). "We also generated 2 human sarcoma cell lines from the 143B sarcoma parent line, 1 with CRISPR ATRX deletion and 1 without, using the identical procedure as above." (PMID 37200088, 2023). "In the undifferentiated sarcoma cohort, TPSB2 expression is decreased when ATRX is altered (based on RNAseq analysis) without reaching significance (p = 0.32)." (PMID 33946962, 2021). "When ATRX is absent from tumors, their transcriptomes are modified toward a lower expression of muscle-related genes in LMS and of immune-related genes in poorly differentiated sarcomas." (PMID 33946962, 2021).
diffuse astrocytoma (27 papers, 2014 to 2025). A low-grade (WHO grade II) astrocytic neoplasm. "An ATRX mutation is usually found in diffuse astrocytomas, generally exclusive to the 1/19q co-deletion." (PMID 34648115, 2021). "IDH1 mutation and ATRX loss: Among seven patients with diffuse astrocytomas who had testing for IDH1 mutations performed on paired surgical specimens, two (29%) patients tested positive at diagnosis and remained positive at recurrence." (PMID 33153497, 2020). "Mutations in IDH1/2 are a defining feature of diffuse astrocytomas and are almost always found in conjunction with inactivating mutations in ATRX and TP5314–17." (PMID 30087349, 2018). "In contrast, diffuse astrocytoma and anaplastic astrocytoma are positive for IDH1 mutations and show loss of ATRX nuclear staining." (PMID 39295729, 2024). "Additional somatic alterations included BRAF p.V600E mutation in the pleomorphic xanthoastrocytoma and PTPN11, ATRX, and NF1 mutations in the diffuse astrocytoma." (PMID 28699883, 2017). "Given the low incidence of ATRX mutations in IDH-wildtype diffuse astrocytomas arising in adults, it was predicted that none of these cases would have ATRX loss by IHC or Foundation Medicine." (PMID 36397144, 2022). "As a complement for diffuse astrocytoma diagnosis, anti-ATRX was used." (PMID 35363819, 2022). "Tumors with loss of ATRX expression and IDH1/2 mutations can be reliably classified as diffuse astrocytomas while IDH1/2 mutant tumors with retained ATRX expression should undergo testing for 1p/19q co-deletion to help differentiate between a diffuse astrocytoma and oligodendroglioma." (PMID 29359122, 2017). "In the diffuse astrocytoma, we show that the germline CDKN2A/B deletion was accompanied by somatic loss of the remaining CDKN2A/B alleles as well as an activating hotspot mutation in PTPN11 and inactivating frameshift mutations in the ATRX and NF1 tumor suppressor genes." (PMID 28699883, 2017). "The tumor was diagnosed post-surgery as a grade II diffuse astrocytoma, IDH1-wild type, ATRX-deleted." (PMID 33222010, 2021). "As ATRX mutations have been to date not detected in pilocytic astrocytomas, ATRX expression analysis might be helpful in diagnostically challenging small biopsies, especially with regard to the differential diagnosis of pilocytic versus diffuse astrocytoma." (PMID 24559763, 2014). "Nuclear ATRX expression was retained, and IDH1 R132H immunostaining was negative, suggesting diagnosis of a pilocytic astrocytoma and arguing against an isocitrate dehydrogenase (IDH)-mutant diffuse astrocytoma." (PMID 41458616, 2025).